RPS6KA6 (ribosomal protein S6 kinase A6)
Synonyms: S6K-alpha-6; p90RSK6; RSK-4; RSK4; PP90RSK4
Tractability: Small molecule: a drug acting on it is in phase 1 trials; a structure with a bound ligand is known; a high-quality ligand is known; it belongs to a druggable protein family. PROTAC: it is named in the literature on targeted protein degradation; ubiquitination databases record sites on it; a small molecule that binds it is known.
Target class: Enzyme; Kinase; AGC protein kinase group; AGC protein kinase RSK subfamily; Protein Kinase; AGC protein kinase RSK family
Chemical probes: BI-D1870
Gene: Protein-coding gene on chromosome X (84,058,346 to 84,206,356, reverse strand). Ensembl gene ENSG00000072133.
Subcellular location: Cytoplasm, cytosol; Nucleus
Subcellular location (Human Protein Atlas): Mitochondria; Nucleoplasm; Nucleoli
Pathways (Reactome):
Neuronal System: CREB1 phosphorylation through NMDA receptor-mediated activation of RAS signaling; RSK activation
Developmental Biology: Recycling pathway of L1
Gene Ontology:
Molecular function: protein binding; protein kinase activity; ribosomal protein S6 kinase activity; ATP binding; magnesium ion binding; protein serine kinase activity; protein serine/threonine kinase activity
Biological process: central nervous system development; negative regulation of embryonic development; negative regulation of ERK1 and ERK2 cascade; negative regulation of mesoderm development; signal transduction; TORC1 signaling; intracellular signal transduction
Cellular component: nucleoplasm; cytosol; nucleus
Homologues: Orthologues: macaque RPS6KA6 (97% identical), chimpanzee RPS6KA6 (97% identical), pig RPS6KA6 (95% identical), dog RPS6KA6 (95% identical), rat Rps6ka6 (88% identical), mouse Rps6ka6 (88% identical), rabbit RPS6KA6 (86% identical), tropical clawed frog rps6ka6 (86% identical), zebrafish rps6kal (84% identical), Caenorhabditis elegans rskn-2 (36% identical), Drosophila melanogaster JIL-1 (33% identical), Caenorhabditis elegans rsks-1 (26% identical), and 3 more. Paralogues in human: RPS6KA3 (76% identical), RPS6KA2 (73% identical), RPS6KA1 (72% identical), RPS6KA5 (44% identical), RPS6KA4 (40% identical), RPS6KB1 (30% identical), RPS6KB2 (27% identical).
Diseases named in the same sentence as RPS6KA6 in open-access papers:
RPS6KA6 is named in the same sentence as 45 diseases in open-access papers, as found by Europe PMC text mining. Sharing a sentence is not in itself a finding about the gene and the disease. The quoted sentences say what the papers report.
breast carcinoma (16 papers, 2013 to 2024). "Firstly, overexpression of ribosomal S6 kinases RPS6KA2 (RSK3) and RPS6KA6 (RSK4) promoted breast cancer growth upon PI3K inhibition treatment, which can be reversed by addition of MEK- or RSK-specific inhibitors." (PMID 33790792, 2021). "In contrast, RPS6KA6 works as a tumor suppressor in endometrial cancer, acute myeloid leukemia, ovarian cancer, and breast cancer." (PMID 34034705, 2021). "RPS6KA6 has been significantly down-regulated in colorectal cancer, ovarian cancer, non-small cell lung cancer, breast cancer, acute myeloid leukemia, etc., while this study is the first to mention that RPS6KA6 is significantly down-regulated in PTC." (PMID 32299435, 2020).
esophageal squamous cell carcinoma (5 papers, 2021 to 2026). Esophageal squamous cell carcinoma (ESCC) is a type of esophageal carcinoma (EC) that can affect any part of the esophagus, but is usually located in the upper or middle third. "Esophageal squamous cell carcinoma (ESCC) is a very aggressive cancer, and the ΔNp63α/RSK4/GSK-3β axis (RSK4: ribosomal protein S6 kinase A6; GSK: glycogen synthase kinase 3β) plays a pivotal role in radioresistance in ESCC." (PMID 36140189, 2022).
renal cell carcinoma (5 papers, 2018 to 2025). "RPS6KA6 plays a differential role in cancers and was reported to be an oncogene in lung squamous cell carcinoma and renal cell carcinoma." (PMID 34034705, 2021).
endometrial cancer (4 papers, 2012 to 2021). Primary or metastatic malignant neoplasm involving the endometrium (mucous membrane that lines the endometrial cavity). "Furthermore, the low expression of RPS6KA6 was the result of DNA hypermethylation in endometrial cancers." (PMID 34034705, 2021).
esophageal cancer (3 papers, 2020 to 2024). A primary or metastatic malignant neoplasm involving the esophagus. "By the way, RPS6KA6 is also considered a DMG in esophageal cancer." (PMID 32299435, 2020).
mental retardation (3 papers, 2008 to 2024). "RPS6KA6/RSK4 has high expression levels in the brain, and its mutation has been suspected of non-specific intellectual disabilities and developmental delays." (PMID 39194544, 2024).
muscular dystrophy (1 paper, 2023). Muscular dystrophy (MD) refers to a group of more than 30 genetic diseases characterized by progressive weakness and degeneration of the skeletal muscles that control movement. "At the same time, it was found that the expression level of RPS6KA6 was significantly increased in the skeletal muscle of patients with muscular dystrophy." (PMID 38314139, 2023).
Parkinson disease (1 paper, 2023). A progressive degenerative disorder of the central nervous system characterized by loss of dopamine producing neurons in the substantia nigra and the presence of Lewy bodies in the substantia nigra and locus coeruleus. "Interestingly, IgG against RPS6KA6 has been shown to be the most frequently selected autoantibody for predicting ageing and age-related neurodegenerative diseases such as AD and advanced-stage Parkinson’s disease." (PMID 38107644, 2023).
X-linked intellectual disability (1 paper, 2023). An X-linked intellectual deficiency in which not enough information is known, reported or published to indicate whether a gene causes non-syndromic or syndromic presentations. "RPS6KA6 is most abundantly expressed in the brain and kidney, and deletions of this protein have been reported to be associated with X-linked intellectual disability." (PMID 38107644, 2023).
cancer (25 papers, 2013 to 2026). A tumor composed of atypical neoplastic, often pleomorphic cells that invade other tissues. "We obtained 74 dysregulated SRGs between normal and cancer tissues, among which six genes (RPS6KA6, ABI3, PTTG1, E2F1, CBX7, and SPOP) were associated with the OS of CC patients." (PMID 37768206, 2023). "RPS6KA6 encodes ribosomal protein S6 kinase A6, a kinase downstream to the ERK/MAPK pathway, and is being investigated as an inhibition target for various cancers." (PMID 35817785, 2022). "It is worth mentioning that RPS6KA6 was considered as a drug resistance marker for the treatment of cancer by protein kinase inhibitors in a study in 2012." (PMID 32299435, 2020). "It is worth further exploring whether the T stage and new cancer events were reversed by regulating LCAT and RPS6KA6." (PMID 34034705, 2021).
tumor (24 papers, 2012 to 2026). "Images of immunohistochemically stained tissue samples showed that RPS6KA6 expressed in normal tissues with medium staining but that it was significantly overexpressed in HCC tumor tissues with high staining." (PMID 36827016, 2023). "Furthermore, LCAT was found to be correlated with T stage and new tumor events, and RPS6KA6 was found to be correlated with T stage." (PMID 34034705, 2021). "Finally, LCAT was found to be correlated with T stage and new tumor events, and RPS6KA6 was found to be related to T stage." (PMID 34034705, 2021). "RPS6KA6 and LCAT were found to be correlated with T (P = 0.015; P = 0.042), and LCAT was significantly related to new tumor events (P = 0.028)." (PMID 34034705, 2021).
RPS6KA6 also shares sentences with these, for which no sentence is quoted: ovarian carcinoma (10 papers); acute myeloid leukemia (7); lung carcinoma (5); clear cell renal cell carcinoma (4); colorectal cancer (4); bladder cancer (3); gastric cancer (3); hepatocellular carcinoma (3); thyroid cancer (3); kidney cancer (2); malignant melanoma (2); adenocarcinoma (1); bladder urothelial carcinoma (1); brain cancer (1); chromosomal disorder (1); colon cancer (1); colorectal adenoma (1); developmental delays (1); glioma (1); leukemia (1); lung adenocarcinoma (1); lung squamous cell carcinoma (1); lymph node metastasis (1); Lynch syndrome (1); metastasis (1); nodular melanoma (1); non-small cell lung carcinoma (1); pancreatic tumors (1); prostate adenocarcinoma (1); prostate carcinoma (1).
A further 4 diseases each share a sentence with RPS6KA6 in 1 paper.